DPYSL2 (dihydropyrimidinase like 2)
Description:
Plays a role in neuronal development and polarity, as well as in axon growth and guidance, neuronal growth cone collapse and cell migration. Necessary for signaling by class 3 semaphorins and subsequent remodeling of the cytoskeleton. May play a role in endocytosis.
Synonyms: DRP-2; CRMP-2; ULIP-2; CRMP2; ULIP2; DHPRP2; DRP2; N2A3
Tractability: Small molecule: a structure with a bound ligand is known; it has a high-quality binding pocket. Antibody: its Gene Ontology location is reachable by antibodies, with high confidence; the Human Protein Atlas places it where antibodies can reach. PROTAC: ubiquitination databases record sites on it; its protein half-life has been measured.
Gene: Protein-coding gene on chromosome 8 (26,514,031 to 26,658,178, forward strand). Ensembl gene ENSG00000092964.
Subcellular location: Cytoplasm, cytosol; Cytoplasm, cytoskeleton; Membrane
Subcellular location (Human Protein Atlas): Cytosol; Microtubules; Cytokinetic bridge; Mitotic spindle; Plasma membrane; Primary cilium
Pathways (Reactome):
Developmental Biology: CRMPs in Sema3A signaling; Recycling pathway of L1
Gene Ontology:
Molecular function: identical protein binding; protein binding; dihydropyrimidinase activity; hydrolase activity; hydrolase activity, acting on carbon-nitrogen (but not peptide) bonds
Biological process: endocytosis; cytoskeleton organization; nervous system development; nucleobase-containing compound metabolic process; pyrimidine nucleobase catabolic process; signal transduction
Cellular component: cytosol; extracellular exosome; intercellular bridge; membrane; microtubule; microtubule cytoskeleton; mitotic spindle; cytoplasm; cytoskeleton
Genetic constraint (gnomAD): Loss-of-function variants: 11 observed, 62.75 expected, observed/expected ratio (o/e) 0.18, 90% interval 0.11 to 0.29. The upper end of that interval is the gene's LOEUF score, 0.29, which puts it in group 1 of 6, group 1 being the genes least tolerant of losing a copy. Missense variants: 547 observed, 863.61 expected, observed/expected ratio (o/e) 0.63, 90% interval 0.59 to 0.68. Synonymous variants: 309 observed, 335.67 expected, observed/expected ratio (o/e) 0.92, 90% interval 0.84 to 1.01.
Homologues: Orthologues: chimpanzee DPYSL2 (100% identical), pig DPYSL2 (99% identical), dog DPYSL2 (98% identical), rat Dpysl2 (98% identical), macaque DPYSL2 (96% identical), tropical clawed frog dpysl2 (86% identical), rabbit DPYSL2 (82% identical), mouse Dpysl2 (82% identical), guinea pig DPYSL2 (74% identical), zebrafish dpysl2b (71% identical). Paralogues in human: DPYSL3 (70% identical), CRMP1 (68% identical), DPYSL4 (63% identical), DPYS (45% identical), DPYSL5 (43% identical).
Diseases named in the same sentence as DPYSL2 in open-access papers:
DPYSL2 is named in the same sentence as 124 diseases in open-access papers, as found by Europe PMC text mining. Sharing a sentence is not in itself a finding about the gene and the disease. The quoted sentences say what the papers report.
schizophrenia (41 papers, 2010 to 2025). A major psychotic disorder characterized by abnormalities in the perception or expression of reality. "Accordingly, genetic linkage studies on humans and behavioural studies on mice have associated the CRMP2 protein (also called DPYSL2) with abnormal behaviour related to the schizophrenia spectrum and other psychiatric disorders." (PMID 32376856, 2020). "Subsequently, genetic association studies in different ethnicities have consistently shown the role of DPYSL2 in schizophrenia susceptibility." (PMID 31591136, 2019). "CRMP2, encoded by the DPYSL2 gene, maps to the chromosome 8p21.2, which has been identified as schizophrenia susceptibility loci in genome-wide linkage studies." (PMID 31591136, 2019). "The relationship between the DPYSL2 gene and susceptibility to schizophrenia was recently confirmed in vivo in rats exposed to prenatal stress (PNS), which indeed is frequently reported as an environmental risk factor for developing schizophrenia in adults." (PMID 30061532, 2018). "Several DPYSL2 single-nucleotide polymorphisms (SNPs) have been associated with the development to schizophrenia." (PMID 30061532, 2018). "DPYSL2 gene has also been associated with susceptibility to psychiatric disorders, such as schizophrenia, or with psychiatric comorbidity, as shown in Alzheimer’s disease." (PMID 30274397, 2018). "Another identified susceptibility gene for schizophrenia is the dihydropyrimidinase-like 2 (DPYSL2) gene." (PMID 30061532, 2018). "Among these six CpG-regulating genes, DPYSL2 is known to be associated with schizophrenia and bipolar disorder; while TCN2 is associated with various disorders including Alzeimer’s disease, vascular disease, and certain cancers (e.g., brain and colorectal)." (PMID 27326381, 2016). "We previously reported a schizophrenia-associated polymorphic CT di-nucleotide repeat (DNR) at the 5′-untranslated repeat (UTR) of DPYSL2, which responds to mammalian target of Rapamycin (mTOR) signaling with allelic differences in reporter assays." (PMID 27801893, 2016). "Functional schizophrenia-associated DPYSL2 variant affects mTOR signaling and has an impact on cellular phenotypes." (PMID 27801893, 2016). "For example, two local CpG sites in body regions were associated with the expression levels of DPYSL2, which is known to be associated with psychiatric disorders including schizophrenia and bipolar disorder." (PMID 27326381, 2016). "The present study investigated a novel target, DPYSL2, to examine the pathophysiology of schizophrenia using proteomic analyses in a PNS animal model associated with the neurodevelopmental theory of schizophrenia." (PMID 25847191, 2015). "The upstream and missense SNPs of the PNS-associated gene DPYSL2 exhibit clear alterations in genetic studies of human patients with schizophrenia." (PMID 25847191, 2015). "In conclusion, the neurodevelopmental theory of schizophrenia and susceptibility to schizophrenia appear to connect the DPYSL2 gene with the disease as the present results suggest DPYSL2 and its SNPs in the pathophysiology of schizophrenia." (PMID 25847191, 2015). "Our results suggest that reduced transcription and mTOR-regulated translation of certain DPYSL2 isoforms increase the risk for schizophrenia." (PMID 25416705, 2014). "Numerous linkage and association studies by our group and others have implicated DPYSL2 at 8p21.2 in schizophrenia." (PMID 25416705, 2014). "Both DPYSL2 and mTOR are associated with common physiological functions such as neuronal polarity, axonal outgrowth and synaptic strength as well as brain disorders including schizophrenia." (PMID 37144098, 2023). "Moreover, brain-specific Dpysl2-KO mice display hyperactivity and social, cognitive and affective behavioral impairments, reminiscent of deficits associated with schizophrenia." (PMID 37144098, 2023).
schizophrenia (continued). "Converging evidence in regard to DPYSL-2 and the risk of schizophrenia have led researchers to hypothesize that the development of the disorder could be related to decreased amounts of DPYSL2 (Phamet al.2016)." (PMID 36317086, 2022). "Additionally, DPYSL2 is located on chromosome 8p21, a region that has been associated with schizophrenia in genetic linkage studies." (PMID 25847191, 2015). "Taken together with previous studies investigating the association between the DPYSL2 gene and schizophrenia, the present findings may contribute additional evidence regarding developmental theories of the pathophysiology of schizophrenia." (PMID 25847191, 2015). "Taken together with functional positional evidence, the present experimental results indicate that mutations or polymorphisms in and/or nearby the DPYSL2 gene may play a role in genetic susceptibility for and development of schizophrenia." (PMID 25847191, 2015). "The present findings demonstrated that the downregulation of genes such as Dpysl2 and Dypsl3 in a rat model of prenatal stress may affect subsequent behavioral changes and that polymorphisms of the DPYSL2 gene in humans may be associated with the development of schizophrenia." (PMID 25847191, 2015). "Thus, the association between the functional SNPs of DPYSL2 and schizophrenia was examined." (PMID 25847191, 2015). "The expression of DPYSL2 in humans has been reported to be decreased in the brains of patients with schizophrenia." (PMID 25394395, 2015). "In this study, DPYSL2 was shown to be affected by the PNS paradigm and was associated with the neurodevelopmental theory of schizophrenia." (PMID 25847191, 2015). "Dpysl2 is affected in schizophrenia, Alzheimer's disease, and Parkinson disease and is upregulated following brain ischemia." (PMID 23738220, 2013). "For instance, MBP and CRMP2/DPYSL2 were previously found differentially expressed in human schizophrenia brain tissue, as well as lanthionine synthetase-like protein." (PMID 20714314, 2010). "Taken together, these data suggest that deregulation of the mTor-DPYSL2 molecular pathway may be involved in NDDs such as schizophrenia or ID." (PMID 37144098, 2023). "DPYSL2 plays a crucial role in the pathogenesis of the serious mental illness schizophrenia." (PMID 36450447, 2023). "In addition to the downregulation of DPYSL-2, schizophrenia-like behaviors were noted in the prenatally stressed offspring (Leeet al.2015)." (PMID 36317086, 2022). "INA and DPYSL2 have been found differentially expressed in schizophrenia brains." (PMID 22350622, 2012). "However, psychotic schizophrenia-like symptoms have also been noted amongst Huntington's disease patients consistent with the interaction of huntingtin with proteins from other schizophrenia-associated genes such as PCM1, PDE4B and DPYSL2." (PMID 21298101, 2011). "Furthermore, altered Dpysl2 activity is related to schizophrenia in an animal model." (PMID 37670703, 2023). "In addition, the 5′‐UTR of DPYSL2 interacts with mTOR effectors in schizophrenia." (PMID 36621846, 2023). "Overall results reveal that impairments in DPYSL2, DPYSL3 and DPYSL5 functions can lead to ID, ASD or schizophrenia." (PMID 37144098, 2023). "Our results support the functional importance of the DPYSL2 DNR and a role for mTOR signaling in schizophrenia." (PMID 27801893, 2016). "To expand our understanding of Schizophrenia and investigate the role of environmental stressors regulating the expression of UNC-33/CRMP2/DPYSL2, we examined the activity of theunc-33promoter under conditions of increasing temperatures and pathogenic infection." (PMID 36317086, 2022). "Moreover, DPYSL2/CRMP2, a microtubule-binding phosphoprotein involved in schizophrenia pathogenesis, was identified as a key factor involved in the NSC differentiation into neurons, promoted by PNS administration." (PMID 32299503, 2020).
schizophrenia (continued). "The absence of DPYSL2 expression may trigger neurodevelopmental disorders including unregulated axon growth and branching, indicating its crucial role in the pathogenesis of schizophrenia." (PMID 32299503, 2020).
Alzheimer disease (32 papers, 2013 to 2026). A progressive, neurodegenerative disease characterized by loss of function and death of nerve cells in several areas of the brain leading to loss of cognitive function such as memory and language. "GWAS data have uncovered several significant single nucleotide polymorphisms (SNPs) within DPYSL2, such as rs2270641, which are linked to heightened risk for Alzheimer’s disease (AD), Parkinson’s disease (PD), and traumatic brain injury (TBI)." (PMID 39532785, 2024). "The hyperphosphorylation of DPYSL2 may induce neuronal apoptosis in the development of Alzheimer’s disease." (PMID 32299503, 2020). "DPYSL2 may also be a key player in the development of Alzheimer’s disease." (PMID 36450447, 2023).
depression (16 papers, 2012 to 2025). "BDNF, which is known to blocks phosphorylation of DPYSL2 via the PI3-kinase/AKt/GSK3-β pathway, is decreased in the brain and serum of patient with depression." (PMID 27104521, 2016).
breast carcinoma (15 papers, 2013 to 2026). "DPYSL2 is extremely highly associated with breast cancer, which can be expressed in breast cancer cells through axonal guidance." (PMID 37409245, 2023). "In a previous study utilizing GENI, we identified that the expression level of the adaptor protein dihydropyrimidines like-2 (DPYSL2) in breast cancer patients correlated with the EMT markers." (PMID 38034403, 2023). "Studies have shown that DPYSL2 affects tumor cell migration via its effect on microtubules; however, it impedes stemness and metastasis of breast cancer cells when combined with RECK." (PMID 34517904, 2021). "JAK1 also interacts with DPYSL2 to promote breast cancer cell migration." (PMID 41511940, 2026). "We can also use DPYSL2 to inhibit breast cancer progression and metastasis by inducing reversal." (PMID 37409245, 2023). "Previous studies have shown that DPYSL2 is differentially expressed in various tumors, with increased expression in non-small cell lung cancer (NSCLC) and colorectal carcinoma and decreased expression in breast cancer." (PMID 34295887, 2021). "Dihydropyrimidinase-related protein 2 (DPYSL2), also known as collapsin response mediator protein 2 (CRMP2), belongs to the CRMP family that shares about 50–70% sequence homology, promoting tumor progression in multiple cancer types, including gastric cancer, colon cancer, and breast cancer." (PMID 34295887, 2021).
glioblastoma (15 papers, 2014 to 2025). The most malignant astrocytic tumor (WHO grade IV). "We demonstrate the potential use of NAP1L1, NUCL, CRMP1, ACTB, and VIM for differentiation between glioblastoma and lower grade gliomas, with DPYSL2 as a promising “glioma versus reference” biomarker." (PMID 28498803, 2017). "DPYSL2 is overexpressed in glioblastoma stem cells, and its inhibition may have potential antitumor effects." (PMID 40869314, 2025). "DPYSL2 plays an important role in axon growth and has oncogene effect in glioblastoma." (PMID 36621846, 2023). "Through bioinformatics analysis, several molecules, including dihydropyrimidinase-related protein 2 (DPYSL2), were identified that are expressed differentially in glioblastoma as compared to normal tissues, providing promising reference biomarkers for follow-up research and treatment." (PMID 36426363, 2022).
neuroblastoma (10 papers, 2012 to 2024). Neuroblastoma (NB) is the most common solid, extracranial childhood tumor. "Dihydropyrimidinase-like 2, namely collapsin response mediator protein-2 (CRMP-2), was implicated in the development of nervous system and highly expressed in mouse neuroblastoma Neuro2a cell lines." (PMID 31043929, 2019).
colorectal carcinoma (9 papers, 2014 to 2025). A malignant epithelial neoplasm that arises from the colon or rectum and invades through the muscularis mucosa into the submucosa. "Higher concentrations of DPYSL2 have been reported in tumor tissues compared with surrounding tissue, as well as in colorectal carcinoma." (PMID 40869314, 2025). "DPYSL2 had been identified as a colorectal carcinoma biomarker." (PMID 29514686, 2018).
bladder cancer (5 papers, 2021 to 2025). "To explore the function of DPYSL2 in bladder cancer progression, we performed gain- and loss-of-function assays." (PMID 34295887, 2021). "To further investigate the mechanism underlying the functions of DPYSL2 in bladder cancer, we performed proteomic analysis to identify the interacting partners of DPYSL2." (PMID 34295887, 2021). "To explore the role of DPYSL2 in bladder cancer progression, we performed gain- and loss-of-function assays in 5637 and T24 cell lines." (PMID 34295887, 2021). "To explore the association of DPYSL2 expression with bladder cancer staging and prognosis, we downloaded corresponding information from multiple databases." (PMID 34295887, 2021). "Together, these results suggest that DPYSL2 upregulation is associated with tumor staging and poor prognosis in bladder cancer patients." (PMID 34295887, 2021). "To investigate the molecular mechanisms underlying the enhancive role of DPYSL2 in bladder cancer progression, we performed a proteomics assay to identify the proteins that physically interact with DPYSL2." (PMID 34295887, 2021). "This study aimed to investigate the function and the underlying mechanism of dihydropyrimidinase like 2 (DPYSL2) in bladder cancer progression." (PMID 34295887, 2021). "Interestingly, DPYSL2 was also classified as one of 12 genes significantly associated with the prognosis of bladder cancer patients, and its high expression is associated with a favorable prognosis in bladder cancer patients." (PMID 40137900, 2025). "Moreover, DPYSL2 deficiency inhibited the malignant behavior and epithelial–mesenchymal transition in bladder cancer cells, thus the downregulation of DPYSL2 observed in the UBT after RTX administration may suggest the anti-cancer properties of the toxin." (PMID 40137900, 2025). "It has been revealed that DPYSL2 was significantly upregulated in urinary bladder cancer compared to normal tissue, and the higher the expression, the more advanced the cancer stage." (PMID 40137900, 2025). "This is the first report regarding the enhancive role of the DPYSL2/PKM2 axis in bladder cancer progression, providing the DPYSL2/PKM2 axis as a promising therapeutic target in bladder cancer treatment." (PMID 34295887, 2021). "Proteomic analysis was performed to identify the interacting partner of DPYSL2 in bladder cancer cells." (PMID 34295887, 2021). "The expression pattern of DPYSL2 in bladder cancer and the correlation of DPYSL2 expression with clinicopathological characteristics of bladder cancer patients were analyzed using the data from different databases and tissue microarray." (PMID 34295887, 2021). "In this study, we demonstrated that the upregulation of DPYSL2 expression correlated with cancer staging and poor prognosis in patients with bladder cancer." (PMID 34295887, 2021). "DPYSL2 promoted bladder cancer cell proliferation, migration, invasion, and colony formation in vitro, as well as xenograft tumor growth and lung metastasis in vivo." (PMID 34295887, 2021). "The results showed that DPYSL2 expression was upregulated in bladder cancer tissue compared with adjacent normal bladder tissue and in more aggressive cancer stages compared with lower stages." (PMID 34295887, 2021). "Functionally, DPYSL2 promoted the malignant behavior of bladder cancer cells in vitro and tumor growth and distant metastasis in vivo." (PMID 34295887, 2021). "DPYSL2 promoted malignant behavior of bladder cancer cells in vitro, as well as tumor growth and distant metastasis in mice." (PMID 34295887, 2021). "Then, we sought to verify the expression pattern of DPYSL2 in different stages of bladder cancer at the protein level." (PMID 34295887, 2021). "Gain- and loss-of-function assays were performed to explore the role of DPYSL2 in bladder cancer progression in vitro and in mice." (PMID 34295887, 2021). "Collectively, these data suggest that DPYSL2 promotes bladder cancer progression and metastasis in vitro and in vivo." (PMID 34295887, 2021).